FGF14 (fibroblast growth factor 14)
Diseases named in the same sentence as FGF14 in open-access papers (continued):
Sharing a sentence is not in itself a finding about the gene and the disease.
Ataxia (continued). "In this study, to explore the possible involvement of expanded GAA repeats in MSA, we investigated the frequencies of expanded GAA repeats in FGF14 in 548 patients with MSA, 476 patients with undiagnosed ataxia, and 455 healthy individuals." (PMID 39604554, 2025). "At the time of MSA diagnosis, the cardinal clinical features in the seven FGF14 GAA≥300 cases consisted of a combination of autonomic failure plus parkinsonism and autonomic failure plus cerebellar ataxia (data missing in one case)." (PMID 40239008, 2025). "In our cohort, patients with MSA carrying an FGF14 GAA≥250 repeat expansion exhibited a combination of autonomic failure, cerebellar ataxia and extrapyramidal symptoms, aligning with the classical MSA phenotype." (PMID 40239008, 2025). "More recently, intronic repeat expansions in RFC1 (cerebellar ataxia, neuropathy, and vestibular areflexia syndrome, CANVAS) and FGF14 (SCA27B) have been identified as more significant causes of adult-onset ataxia than previously appreciated." (PMID 38132285, 2023). "However, it remains to be determined whether parallel fibers (PF) to Purkinje neuron synapses, the primary output of cerebellar circuit and the most vulnerable synaptic connection in ataxias, are affected by genetic deletion of Fgf14 and exhibit any phenotype consistent with in vitro studies." (PMID 26089778, 2015). "We did not observe a correlation between the age‐at‐onset of ataxia and the number of repeats in FGF14, consistent with other studies reported to date." (PMID 40191983, 2025). "Ataxia can be mild or absent despite deletion of exon 4 and 5 in FGF14, while deletion in exons 1–3 did result in ataxia, suggesting some genotype-phenotype correlations in SCA27A." (PMID 41099962, 2025). "Frequency of FGF14 GAA repeat expansions was 38% (17/45) in the entire cohort, 38% (5/13) in the subgroup with cerebellar ataxia plus polyneuropathy, 43% (9/21) in the subgroup with cerebellar ataxia plus BVP and 27% (3/11) in patients with all three features." (PMID 37399286, 2024). "Our study demonstrates that FGF14 GAA repeat expansions are common in patients negative for biallelic RFC1 repeat expansions presenting with a combination of cerebellar ataxia plus polyneuropathy and/or BVP." (PMID 37399286, 2024). "In a recent study, FGF12 single-KO mice showed no phenotype, while FGF12/FGF14 double-KO mice developed severe ataxia and decreased neuronal excitability." (PMID 30065296, 2018). "Importantly, none of the FGF14 GAA≥250 cases presented with cerebellar ataxia with autonomic failure alone (in the absence of parkinsonism) compared with the non-expanded group (21.9%) (P = 0.04, adjusted P = 0.06)." (PMID 40239008, 2025). "Here, we studied the frequency of FGF14 GAA repeat expansions in patients with a combination of cerebellar ataxia plus peripheral neuropathy and/or BVP negative for biallelic RFC1 repeat expansions, and report on the phenotypic spectrum of GAA-FGF14-positive patients." (PMID 37399286, 2024). "While FGF14 GAA repeat expansions have recently been shown to be a common cause of spinocerebellar ataxia (SCA27B)—which is associated with DBN in up to 40–60% of patients—, the high frequency of FGF14 (GAA)≥250 repeat expansions in patients with a non-ataxic DBN presentation was unexpected." (PMID 38507876, 2024). "Heterozygous FGF14 variants are associated with spinocerebellar ataxia type 27 (SCA27) and episodic ataxia (EA), although some individuals display milder phenotypes, including tremor without ataxia or nystagmus with occasional episodes of vertigo and incoordination." (PMID 36207621, 2023). "Furthermore, a higher proportion of cases with dual pathology compared with FGF14-negative MSA cases presented with a mixed phenotype of parkinsonism and cerebellar ataxia (11.8%) compared with MSA patients without the FGF14 expansion (1.04%) (P = 0.05, adjusted P = 0.06)." (PMID 40239008, 2025).
spinocerebellar ataxia 27 (16 papers, 2014 to 2025). "FGF14 mutations are considered a rare cause of spinocerebellar ataxia type 27 (SCA 27) and show a broad phenotypic spectrum." (PMID 36353133, 2022). "Originally identified as the genetic locus of missense mutations leading to spinocerebellar ataxia type 27, fibroblast growth factor 14 (FGF14) is an emerging risk factor for neuropsychiatric disorders." (PMID 30678040, 2019). "In humans, mutations in FGF14 are mostly associated with spinocerebellar ataxia type 27 (SCA27), part of a diverse group of autosomal dominant hereditary ataxias whereby affected individuals develop progressive incoordination." (PMID 29253853, 2017). "Genetically inherited mutations in the fibroblast growth factor 14 (FGF14) gene lead to spinocerebellar ataxia type 27 (SCA27), an autosomal dominant disorder characterized by heterogeneous motor and cognitive impairments." (PMID 26089778, 2015). "Spinocerebellar ataxia 27 (SCA27) is associated with pathogenic variants in FGF14 which is situated on chromosome 13q33." (PMID 41099962, 2025). "In addition, mutations in the FGF14 gene cause spinocerebellar ataxia type 27." (PMID 32157568, 2020). "The goal of this study was to characterize a Swedish family with members affected by spinocerebellar ataxia 27 (SCA27), a rare autosomal dominant disease caused by mutations in fibroblast growth factor 14 (FGF14)." (PMID 32112487, 2020). "Fibroblast growth factor 14 (FGF14) is a functionally relevant component of the Nav1.6 channel complex, a causative link to spinocerebellar ataxia 27 (SCA27) and an emerging risk factor for neuropsychiatric disorders." (PMID 31729429, 2019). "In humans, the naturally occurring FGF14F145S mutation results in spinocerebellar ataxia 27 (SCA27), a severe motor and cognitive neurodegenerative disorder, and SNPs in the FGF14 gene have been associated with depression and schizophrenia." (PMID 25659151, 2015). "As an example, we used Fibroblast Growth Factor 14 (FGF14), which is highly expressed in wild type cerebellar Purkinje neurons and in which a mutation causes Spinocerebellar ataxia, type 27 (SCA27) in humans." (PMID 25093726, 2014). "Inherited loss-of-function mutations in the FGF14 coding region disrupt the trafficking of Nav α subunits to the AIS, attenuate Nav current densities, and impair excitability of hippocampal neurons —phenotypes that are thought to contribute to spinocerebellar ataxia 27 (SCA27)." (PMID 35457230, 2022).
episodic ataxia (11 papers, 2017 to 2025). "The patient included here with a mutation in the FGF14 gene is to our knowledge the thirteenth case described with the clinical syndrome of episodic ataxia." (PMID 36353133, 2022). "FGF14‐associated phenotypes emphasize this overlap between progressive and episodic ataxias, with phenotypic continuum encompassing chronic (SCA27) and paroxysmal ataxia." (PMID 32162847, 2020). "Age of onset (AO) and the clinical presentation of SCA27 are variable; other phenotypes than SCA27 associated with mutations in FGF14 include episodic ataxia, paroxysmal chorea, parkinsonism and dysmorphism and/or microcephaly." (PMID 32112487, 2020). "We report four patients from two families who presented attacks of childhood‐onset episodic ataxia associated with pathogenic mutations in the FGF14 gene." (PMID 32162847, 2020). "Main clinical features of patients with paroxysmal neurological manifestations (episodic ataxia, paroxysmal dyskinesia) harboring FGF14 mutation previously reported in the literature." (PMID 32162847, 2020). "Using whole genome sequencing we have discovered a novel nonsense mutation (c.46C>T) in FGF14 leading to a premature stop codon (p.Q16*) in lambs affected with familial episodic ataxia of lambs." (PMID 29253853, 2017). "In addition, lambs affected by episodic ataxia harbouring the mutation c.46C> T in FGF14 lack also gross histopathological abnormalities." (PMID 32112487, 2020). "These cases and literature data delineate the FGF14‐mutation‐related episodic ataxia phenotype: wide range of age at onset (from childhood to adulthood), variable durations and frequencies, triggering factors including fever, and association to chronic symptoms." (PMID 32162847, 2020). "The occurrence of episodic ataxia (EA) has been occasionally associated with FGF14 mutations." (PMID 32162847, 2020). "Familial episodic ataxia of lambs is strongly associated with a c.46C>T variant in the FGF14 gene." (PMID 29253853, 2017). "Here we describe two patients with microdeletions (< 2 Mbp) in FGF14 gene, leading to either adult-onset episodic ataxia, trigeminal neuralgia, and ADHD-autism spectrum disorder or to an infantile episodic movement disorder." (PMID 41099962, 2025). "We identified a family with early onset nystagmus and additional neurological features carrying a partial duplication of FGF14, a gene associated with spinocerebellar ataxia type 27 (SCA27) and episodic ataxia." (PMID 36207621, 2023). "We propose to add FGF14‐related episodic ataxia to the list of primary episodic ataxia as Episodic Ataxia type 9." (PMID 32162847, 2020). "Fibroblastic growth factors (FGFs) and their receptors have been implicated in CNS development (Reuss and von Bohlen und Halbach 2003) as well as diverse neurological diseases, e.g., episodic ataxia (FGF14‐related SCA‐27B) and FGF12, which has been reported in Alzheimer's disease (AD)." (PMID 40406903, 2025). "In FGF14- related episodic ataxia, upper limb postural tremor was frequently noted." (PMID 38911333, 2024). "Nystagmus and/or postural tremor and/or learning disabilities were noticed in individuals harboring FGF14 mutation with or without episodic ataxia." (PMID 32162847, 2020).
Nystagmus (11 papers, 2020 to 2025). Rhythmic, involuntary oscillations of one or both eyes related to abnormality in fixation, conjugate gaze, or vestibular mechanisms. "The observation of a cerebellar syndrome of late-onset associated with episodic symptoms, downbeat nystagmus, and alcohol intolerance should prompt testing for the FGF14 GAA expansion." (PMID 37322040, 2023). "Therefore, our study reveals the genetic variant underlying NYS4, expands the spectrum of pathogenic FGF14 variants, and highlights the importance of screening FGF14 in apparently isolated early onset nystagmus." (PMID 36207621, 2023). "In conclusion, our study identifies the genetic basis of NYS4, expands the spectrum of FGF14 variants, refines the phenotypes of the associated oculomotor anomalies, and demonstrates the value of screening FGF14 in children with apparently isolated early onset nystagmus." (PMID 36207621, 2023). "Given the persistent dysphonia and nystagmus, genetic testing was conducted, revealing a deletion in FGF14 gene (exons 1–3), confirming a diagnosis of Spinocerebellar Ataxia 27 A (ARRAY ISCN: arr[GRCh38] 13q33.1(101732949_102278224)x1)." (PMID 41099962, 2025). "However, the progressive nature of her cerebellar symptoms and the emergence of novel downbeat nystagmus prompted genetic testing for FGF14 repeat expansion, confirming SCA27B as a significant contributor to her delayed, progressive cerebellar symptoms." (PMID 39821862, 2025). "However, since such detailed eye movement evaluation is rarely possible in routine clinical practice, particularly in children, we recommend the inclusion of FGF14 on gene panels for childhood nystagmus." (PMID 36207621, 2023). "The FGF14 mutation was also identified in family members exhibiting a milder phenotype (isolated nystagmus or upper limb postural tremor with childhood‐onset, without EA)." (PMID 32162847, 2020).
schizophrenia (10 papers, 2012 to 2025). A major psychotic disorder characterized by abnormalities in the perception or expression of reality. "While preclinical studies linking FGF14 haploinsufficiency to ADHD are limited, there is evidence associating FGF14 with autism and schizophrenia." (PMID 41099962, 2025). "Since one patient presents with a psychotic disorder, an exploratory study of markers of schizophrenia associated with GABAergic neurotransmission was performed in fgf14−/− mice, a preclinical model that replicates motor and learning deficits of SCA27." (PMID 32112487, 2020). "We previously demonstrated that male Fgf14−/− mice recapitulate the salient endophenotypes of synaptic dysfunction and behaviors that are associated with schizophrenia (SZ)." (PMID 30678040, 2019). "GWAS in German cohort found an association between FGF14 and schizophrenia, which is corroborated by a linkage study of familial schizophrenia in Canadian families of Celtic or German descent." (PMID 28469558, 2017). "Both WEE1 and FGF14 have been associated with schizophrenia and other neurodevelopmental disorders." (PMID 39125637, 2024). "Moreover, our findings are in accordance with the fact that polymorphisms in FGF14 have emerged as significant risk factors not only for schizophrenia but also for other psychiatric conditions." (PMID 32112487, 2020). "Studies focused on signaling pathways demonstrated that FGF14 is also a hub for regulatory kinases, including glycogen synthase kinase 3, which is an enzyme that is linked to depression, bipolar disorder, and schizophrenia (SZ)." (PMID 30678040, 2019). "Since then, FGF14 has been indicated by several linkage and genome wide association studies (GWAS) to be a putative risk factor for other neuropsychiatric diseases including depression, addiction and schizophrenia, as well as neurodegenerative diseases, such as Alzheimer’s Disease." (PMID 28469558, 2017). "Thus, diminished expression of FGF14 in humans might be a risk factor for complex brain diseases associated with cognitive impairment such as schizophrenia." (PMID 27163207, 2016). "Thus, WEE1 may be part of a signaling pathway, including FGF14 and Nav1.2, that, if perturbed, could contribute to endophenotypes related to neurodevelopmental disorders such as schizophrenia and SCN2A channelopathies associated with autism spectrum disorder and epilepsy." (PMID 39125637, 2024). "Overall, deletion of FGF14 results in an immature dentate gyrus, an endophenotype that corroborates a link between the gene and schizophrenia." (PMID 28469558, 2017). "A Brazilian pilot study on early onset/familial schizophrenia found a link between early-onset schizophrenia and FGF14." (PMID 28469558, 2017). "Bioinformatics analysis of schizophrenia transcriptomics revealed functional co-clustering of FGF14 and genes enriched within the GABAergic pathway along with correlatively decreased expression of FGF14, PVALB, GAD67 and VGAT in the disease context." (PMID 27163207, 2016). "The absence of the FGF14 gene in knockout mice led to aberrant sodium channel signaling, as well as dysfunction and behaviors associated with schizophrenia and other neurological disorders." (PMID 33920138, 2021). "Collectively, these results recapitulate some endophenotypes of schizophrenia and are supported by human studies finding significant reduction and co-variation of FGF14, PV, vGAT and GAD67 in post-mortem samples from schizophrenic patients compared to healthy control individuals." (PMID 28469558, 2017). "In addition, reduced expression of VGAT, a presynaptic component of inhibitory synapses and a marker of schizophrenia, was found in the medial prefrontal cortex (mPFC) of fgf14−/− mice, an animal model of SCA27 which replicates motor and cognitive features of the disease." (PMID 32112487, 2020).
schizophrenia (continued). "Additionally, in the same study bioinformatics analysis of schizophrenia transcriptomics revealed functional co-clustering of FGF14 and genes enriched within the GABAergic pathway along with correlatively decreased expression of FGF14 and VGAT in the disease context." (PMID 32112487, 2020). "Bioinformatics analysis from human transcriptomics identified FGF14 as a component of GABAergic synaptic signaling and revealed a correlated decrease in FGF14, PVALB, GAD67 and VGAT gene expression in schizophrenia post-mortem tissues compared with matched controls." (PMID 27163207, 2016). "This phenotype is consistent with a diminished total pool of the two proteins, which might result from covariance of FGF14, GAD67 and VGAT at expression level as suggested by our bioinformatics analysis from schizophrenia samples." (PMID 27163207, 2016). "Human transcriptomics data confirmed functional clustering of FGF14 with GABAergic signaling and identified a highly correlated decrease of FGF14, PVALB, GAD67 and VGAT in schizophrenia post-mortem tissues, indicating possible genetic co-regulation of these genes." (PMID 27163207, 2016).
Cognitive impairment (9 papers, 2014 to 2025). Abnormal cognition is characterized by deficits in thinking, reasoning, or remembering. "Deletions affecting FGF14 exons 1–3 are consistently associated with cognitive impairment, as evidenced by multiple cases of intellectual disability and progressive cognitive decline, including in the wider family." (PMID 41099962, 2025). "FGF14 homozygous knockout mice exhibit abnormal synaptic plasticity, reduced neurogenesis in the hippocampus, and impaired spatial learning, linking FGF14 loss to cognitive impairment in the SCA27 phenotype." (PMID 41099962, 2025). "Importantly, we found that many of the proteins differentially expressed in male Fgf14−/− mice have previously been linked to neuropsychiatric disorders with cognitive impairment, such as SZ and autism." (PMID 30678040, 2019). "Namely, male Fgf14−/− mice present with the loss of parvalbumin positive GABAergic interneurons in the hippocampus, disrupted gamma frequency, and reduced working memory, all of which are hallmarks of cognitive impairment in SZ animal models and post-mortem studies." (PMID 30678040, 2019). "There was less cognitive impairment, as judged clinically, in patients with FGF14 expansions (12%; 13%, and 9%, respectively in SCA27B patients compared to the 40% in the SCA27B-negative group at first examination)." (PMID 39227614, 2024). "Previous work has demonstrated that male Fgf14−/− mice present with cognitive deficits and changes in neuronal function that mimic the endophenotypes of SZ and other neuropsychiatric disorders." (PMID 30678040, 2019). "However, exceptions were reported, where a 200 kbp deletion spanning FGF14 exons 2–5 and ITGBL1 gene and a 168 kbp deletion spanning FGF14 exons 4–5 and ITGBL1 gene, respectively, did not cause cognitive impairment." (PMID 41099962, 2025).
hereditary ataxia (8 papers, 2015 to 2026). An instance of an atactic disorder that is caused by an inherited genomic modification in an individual. "The clinical features of humans with hereditary ataxias and FGF14 mutations are variable, most cases have been diagnosed in young children ranging in age from 8 months to 5 years." (PMID 29253853, 2017). "As complementary evidence of FGF14’s role in human hereditary ataxias, several studies indicate a role of FGF14 in cerebellar function in rodent models." (PMID 32112487, 2020). "Given the recent discovery of a role of metabotropic glutamate receptors in hereditary ataxias, we have examined whether deficits in presynaptic release could impact postsynaptic mGluR1 activation in PC of Fgf14−/− mice." (PMID 26089778, 2015).